DENR (density regulated re-initiation and release factor)
Description:
Translation regulator forming a complex with MCTS1 to promote translation reinitiation. Translation reinitiation is the process where the small ribosomal subunit remains attached to the mRNA following termination of translation of a regulatory upstream ORF (uORF), and resume scanning on the same mRNA molecule to initiate translation of a downstream ORF, usually the main ORF (mORF). The MCTS1/DENR complex is pivotal to two linked mechanisms essential for translation reinitiation. Firstly, the dissociation of deacylated tRNAs from post-termination 40S ribosomal complexes during ribosome recycling. Secondly, the recruitment in an EIF2-independent manner of aminoacylated initiator tRNA to P site of 40S ribosomes for a new round of translation. This regulatory mechanism governs the translation of more than 150 genes which translation reinitiation is MCTS1/DENR complex-dependent.
Synonyms: DRP; SMAP-3; DRP1
Tractability: Small molecule: a structure with a bound ligand is known. PROTAC: ubiquitination databases record sites on it; its protein half-life has been measured.
Gene: Protein-coding gene on chromosome 12 (122,752,824 to 122,771,064, forward strand). Ensembl gene ENSG00000139726.
Subcellular location: Cytoplasm
Subcellular location (Human Protein Atlas): Cytosol
Gene Ontology:
Molecular function: protein binding; translation initiation factor activity
Biological process: formation of translation preinitiation complex; IRES-dependent viral translational initiation; ribosome disassembly; translation reinitiation; cytoplasmic translational initiation; translational initiation
Cellular component: cytoplasm; translation initiation complex
Genetic constraint (gnomAD): Loss-of-function variants: 3 observed, 13.59 expected, observed/expected ratio (o/e) 0.22, 90% interval 0.1 to 0.57. The upper end of that interval is the gene's LOEUF score, 0.57, which puts it in group 2 of 6, group 1 being the genes least tolerant of losing a copy. Missense variants: 104 observed, 159.6 expected, observed/expected ratio (o/e) 0.65, 90% interval 0.56 to 0.77. Synonymous variants: 60 observed, 52.65 expected, observed/expected ratio (o/e) 1.14, 90% interval 0.93 to 1.41.
Homologues: Orthologues: chimpanzee DENR (100% identical), macaque DENR (99% identical), rabbit DENR (97% identical), dog DENR (96% identical), mouse Denr (96% identical), guinea pig DENR (96% identical), pig DENR (96% identical), rat Denr (95% identical), tropical clawed frog denr (85% identical), zebrafish denr (80% identical), Drosophila melanogaster DENR (46% identical), Caenorhabditis elegans Y47D3A.21 (44% identical).
Diseases named in the same sentence as DENR in open-access papers:
DENR is named in the same sentence as 26 diseases in open-access papers, as found by Europe PMC text mining. Sharing a sentence is not in itself a finding about the gene and the disease. The quoted sentences say what the papers report.
glioma (4 papers, 2016 to 2025). A benign or malignant brain and spinal cord tumor that arises from glial cells (astrocytes, oligodendrocytes, ependymal cells). "SVs identified in the Mastiffs clade intersected with the introns of three genes: ABCB9, PITPNM2, and DENR, that last of which was found to have two intronic deletions and has been implicated in canine glioma susceptibility." (PMID 40971676, 2025). "A locus on canine chromosome (CFA) 26 has been strongly associated with glioma risk across multiple dog breeds, with regional mapping revealing single nucleotide variants in three neighboring genes DENR, CAMKK2, and P2RX7 that are highly associated with glioma susceptibility." (PMID 31788444, 2019).
autism (3 papers, 2016 to 2021). Persistent deficits in social interaction and communication and interaction as well as a markedly restricted repertoire of activity and interest as well as repetitive patterns of behavior. "Last, we explored the connection between ribosome recycling and known DENR mutants that are associated with autism." (PMID 34016977, 2021). "To search for additional DENR mutations in patients with an autism-related diagnosis, we conducted whole-exome sequencing of a patient diagnosed with Asperger syndrome and associated epilepsy to identify a de novo missense (c.362C > T, NM_003677) mutation that results in a p.P121L substitution." (PMID 27239039, 2016). "The identification of DENR and MCTS1 target transcripts will serve as a basis for future studies aimed at understanding the mechanistic involvement of DENR and MCTS1 in cancer and autism." (PMID 28623304, 2017). "The non-canonical initiation factors DENR and MCTS1 have been linked to cancer and autism." (PMID 28623304, 2017).
autism spectrum disorder (2 papers, 2016 to 2017). A spectrum of developmental disorders that includes autism, and Asperger syndrome. "In addition, we have characterized de novo missense mutations to DENR in two unrelated human subjects diagnosed with autism spectrum disorder." (PMID 27239039, 2016). "DENR and MCTS1 are misexpressed or mutated in patients with cancer or autism spectrum disorders." (PMID 28623304, 2017). "This work will likely be a useful starting point for future studies analyzing the functional involvement of DENR and MCTS1 in cancer and autism spectrum disorders." (PMID 28623304, 2017).
breast carcinoma (1 paper, 2019). "For example, DENR and HLA-F were suggested as important players in breast cancer cells." (PMID 30911020, 2019).
cervical cancer (1 paper, 2020). A primary or metastatic malignant neoplasm involving the cervix. "Since we find DENR•MCTS1 is required for ATF4 expression in cervical cancer HeLa cells, leukemia Jurkat cells, and fibrosarcoma HT1080 cells, we postulated DENR•MCTS1 may promote ATF4 translation in many different cancers." (PMID 32938922, 2020).
colon adenocarcinoma (1 paper, 2022). "To test our hypothesis, we knocked out DENR gene in murine colon adenocarcinoma MC38 cells and assayed the protein and mRNA levels of PD-L1 by immunoblot, FACS and RT-qPCR respectively." (PMID 35440133, 2022).
fibrosarcoma (1 paper, 2020). A malignant mesenchymal fibroblastic neoplasm affecting the soft tissue and bone. "Knockdown of DENR and/or eIF2D also reduced ATF4 protein levels in HT1080 fibrosarcoma cells indicating this is not specific to HeLa cells." (PMID 32938922, 2020).
lung carcinoma (1 paper, 2022). "DENR was reported to be a risk gene in lung cancer, and its high expression could inhibit the survival of patients with lung cancer." (PMID 35993327, 2022).
lung squamous cell carcinoma (1 paper, 2020). "Interestingly, ASNS mRNA levels correlate with DENR•MCTS1 levels in individual cancer entities such as liver hepatocellular carcinoma (r > 0.35), lung squamous cell carcinoma (r > 0.5) and renal cancer (r > 0.49), and indeed throughout the entire TCGA pan-cancer set (r > 0.36)." (PMID 32938922, 2020).
melanoma (1 paper, 2022). A malignant, usually aggressive tumor composed of atypical, neoplastic melanocytes. "In addition, we observed a reduction of PD-L1 after DENR KO in murine melanoma B16/F10 cells, suggesting DENR’s general role in reducing PD-L1 expression in different cell lines." (PMID 35440133, 2022). "Furthermore, knocking out DENR in human cancer cell lines, such as human colon HT29 cancer cells and human melanoma A375 cells, also resulted in reduced JAK2 protein levels, indicating that the mechanism of DENR in regulating JAK2 expression is conservative in both murine and human." (PMID 35440133, 2022).
neuronal migration disorder (1 paper, 2016). "Given our MRI studies of the patient harboring a DENR P121L substitution mutation that revealed features consistent with neuronal migration disorder, including nodular heterotopia, we looked for evidence of such a phenotype in our in vivo experiments." (PMID 27239039, 2016).
renal carcinoma (1 paper, 2020). A carcinoma arising from the epithelium of the renal parenchyma or the renal pelvis. "In agreement with this, in cancer entities where ATF4 activity (assayed as ASNS mRNA levels) correlates with survival (e.g. renal cancer and liver hepatocellular carcinoma), also DENR or MCTS1 levels have prognostic value." (PMID 32938922, 2020).
T-cell lymphoma (1 paper, 2023). "The best-known eIF2-less mechanisms replace eIF2 with eIF5B or MCT-1•DENR (multiple copies in T-cell lymphoma • density regulated protein complex)." (PMID 36689548, 2023).
viral infection (1 paper, 2022). "The malignant T cell-amplified sequence 1 forms a heterodimer with DENR (density-regulated protein) and serves as the translation factor which supports noncanonical translation initiation and ribosome recycling linked to cancer, viral infection, and neurological disorders." (PMID 35723340, 2022).
cancer (6 papers, 2016 to 2022). A tumor composed of atypical neoplastic, often pleomorphic cells that invade other tissues. "Similarly, other candidates from our DENR target list are upregulated in (and possibly causally contributing to) different cancers, such as Vascular endothelial growth factor D (VEGF-D) or Mitogen-Activated Protein Kinase 5 (MAP2K5)." (PMID 30982898, 2019). "Many identified DENR targets are involved in proliferation and associated with cancer." (PMID 30982898, 2019). "The results showed that in OVA expressing cancer cells, DENR depletion resulted in weaker p-STAT1 signaling, lower PD-L1 expression, and significant higher percentage of apoptotic cells." (PMID 35440133, 2022). "Among the DENR-regulated transcripts were several relevant to cancer, such as Klhdc8a, Etaa1, Map2k5, Slc20a1 or Vegfd." (PMID 30982898, 2019). "Due to the role of ATF4 in cancer, as well as the role of the other DENR-target genes identified here, this may explain why DENR•MCTS1 have been identified as oncogenes." (PMID 32938922, 2020). "Hence DENR•MCTS1 appear to promote ATF4 translation in a broad range of cancer cells." (PMID 32938922, 2020). "We find that DENR•MCTS1 levels correlate with ASNS mRNA levels, a readout for ATF4 activity, across the TCGA pan-cancer set." (PMID 32938922, 2020). "Moreover, translational reprogramming, especially with regard to upstream initiation sites, appears to represent an important cancer driver, and understanding how the translation of cancer-relevant DENR targets is regulated may thus lead to important insights of diagnostic or therapeutic value." (PMID 30982898, 2019). "This is particularly relevant if the transcript isoform that is DENR•MCTS1 dependent is the only one expressed in a cell, or the only one with cancer-relevant function." (PMID 28623304, 2017). "By identifying the DENR•MCTS1 dependent transcripts in humans, this current study enables future work aimed at understanding how these proteins affect cancer and brain function." (PMID 28623304, 2017). "So far, however, none of these pro-cancer effects of DENR•MCTS1 have been linked to direct translational targets, suggesting additional targets of DENR•MCTS1 remain to be discovered." (PMID 32938922, 2020). "Because DENR inactivation in Drosophila is lethal due to impaired histoblast proliferation, the DENR-MCT-1 complex was suggested to regulate translation of specific mRNAs, presumably from “cancer-relevant” genes, i.e. those involved in cell growth." (PMID 27171399, 2016). "Hence DENR and MCTS1 appear to play a role in cancer biology and in neurobiology." (PMID 28623304, 2017).
tumor (3 papers, 2020 to 2022). "DENR depletion significantly suppresses tumor growth and enhances the tumor-killing activity of CD8+ T cells." (PMID 35440133, 2022). "Together, our data indicate that DENR expression in tumors supports tumor evasion by regulating PD-L1 expression, and DENR KO assists faster tumor immune ejection, suggesting that DENR is a promising immunotherapy target." (PMID 35440133, 2022). "As expected, the DENR KO tumors grew much slower than WT tumors, and the tumor size of the KO cells was much smaller for B16/F10 tumor." (PMID 35440133, 2022). "When analyzed by FACS, the PD-L1 expression levels of DENR KO tumor cells were significantly lower than those of control WT cells." (PMID 35440133, 2022). "A deficiency in DENR leads to decreased JAK2 translation and impairs JAK-STAT signaling, thus reducing PD-L1 expression in tumor cells and repressing tumor growth by enhancing the anti-tumor killing activity of CD8+ T cells in the tumor microenvironments." (PMID 35440133, 2022). "Here the authors show that a RNA binding protein, DENR, positively regulates the translation of JAK2 and induces PD-L1 expression in tumor cells, associated with immune evasion." (PMID 35440133, 2022). "However, the clinical data is limited in our study, and the DENR function in tumor microenvironment of the tumor patients is very complex and is in need of further investigation." (PMID 35440133, 2022). "Overall, we discover an RBP DENR that could regulate PD-L1 expression for tumor immune evasion, and highlight the potential of DENR as a therapeutic target for immunotherapy." (PMID 35440133, 2022). "DENR is highly expressed in multiple tumor types and indicates the poor prognosis of patients." (PMID 35440133, 2022). "Interestingly, we found that the percentage of DENR KO tumor cells in all tumors was similar to that of control WT tumor cells on day 8 but much lower than that of WT tumor cells on day 12, indicative of a specific and faster clearance of DENR KO tumor cells in the same tumor microenvironment." (PMID 35440133, 2022). "Overexpression or copy-number gains of DENR and MCTS1, on the other hand, have been described in several tumor entities." (PMID 35115540, 2022). "We subcutaneously injected DENR KO B16/F10 or MC38 cells into the lower flanks of WT C57BL/6 mice, monitored the daily tumor growth, and sacrificed the mice at the end of the experiment." (PMID 35440133, 2022). "Together, these results suggest that DENR depletion in tumors reduces the expression of PD-L1 upon CD8+ T cell treatment and, thus, enhances CD8+ T cell anti-tumor activities." (PMID 35440133, 2022). "We first showed that DENR depletion did not affect tumor growth in culture dishes by Cell Counting Kit 8 (CCK8) assay (Supplementary 5a, b)." (PMID 35440133, 2022). "Next, to prove that the more efficient killing of DENR KO tumors over WT tumors was indeed due to increased tumor infiltration and enhanced killing of CD8+ T cells, we subcutaneously implanted DENR KO and control cells into the flanks of RAG1−/− mice in which the T cells and B cells were depleted." (PMID 35440133, 2022). "DENR and MCTS1 have been identified as oncogenes in several different tumor entities." (PMID 35115540, 2022).
neurological disease (2 papers, 2016 to 2022). "Characterization of disease-associated mutations in DENR links impaired mRNA translation re-initiation to human neurological disorders." (PMID 27239039, 2016). "Furthermore, we have characterized substitution variants of DENR detected in human subjects with neurological disorders and found that the presence of mutated DENR disrupts its functions in mRNA translation in vitro and is detrimental to the development of cerebral cortical neurons in vivo." (PMID 27239039, 2016).
brain disorder (1 paper, 2016). A disease affecting the brain or part of the brain. "Thus, our findings link human brain disorders to impaired mRNA translation re-initiation through perturbations in DENR (OMIM: 604550) function in neurons." (PMID 27239039, 2016).
infectious disease (1 paper, 2023). A disorder directly resulting from the presence and activity of a microbial, viral, or parasitic agent in humans. "We found no individuals heterozygous or homozygous for pLOF variants of DENR in our own cohort of patients with various infectious diseases, including MSMD." (PMID 37875108, 2023).
DENR also shares sentences with these, for which no sentence is quoted: Asperger syndrome (2 papers); brain tumors (1); epilepsy (1); leukemia (1); neurodevelopmental disorder (1); nodular heterotopia (1); Obesity (1).